SOX2 (SRY-box transcription factor 2)
Diseases named in the same sentence as SOX2 in open-access papers (continued):
Sharing a sentence is not in itself a finding about the gene and the disease.
osteosarcoma (continued). "Additionally, we found that osteosarcoma cells isolated from different patients express variable levels of SOX2 expression and different percentage of SOX2-positive cells." (PMID 28934267, 2017). "Moreover, miR-126 was described as an inhibitor of osteosarcoma proliferation, migration and invasion by suppressing SOX2 expression." (PMID 28934267, 2017). "Moreover, miR-29 negatively regulates the expression of stemness-related markers, such as Oct3/4, Sox2 and Nanog, and subsequently suppresses the proliferation, sphere formation and chemoresistance of human osteosarcoma stem cells." (PMID 27356624, 2016). "Additionally we report a novel mode of action of TZDs in osteosarcoma in promoting the nuclear exclusion of SOX2 and YAP transcription factors." (PMID 27528232, 2016). "In osteosarcoma, we showed that high Sox2 expression marks and maintains tumor-initiating CSCs." (PMID 27528232, 2016). "High Sox2 expression was accompanied by reduced Wnt signaling, while the activation of Wnt signaling resulted in low Sox2 expression, suggesting that the activation of Wnt signaling antagonizes the effect of Sox2 in maintaining osteosarcoma cells." (PMID 28115942, 2016). "Yet, a recent report demonstrated that SOX2 maintains self renewal of murine tumor-initiating osteosarcoma cells which were driven into osteogenic differentiation through increased basal TCF/LEF-signaling after knockdown of SOX2 and lost proliferative capacity." (PMID 22070920, 2011). "Thus, our results indicated that DUSP3 regulates the STAT3/SOX2 axis in osteosarcoma." (PMID 39744427, 2025). "Therefore, we speculated that DUSP3 affects the stemness of osteosarcoma cells by regulating the EGFR/STAT3/SOX2 axis." (PMID 39744427, 2025). "Therefore, we hypothesize that the SOX2/LPCAT1 axis drives osteosarcoma progression by reprogramming cholesterol metabolism, thereby enhancing malignancy and metastatic potential." (PMID 41358198, 2025). "In addition, the proliferation of osteosarcoma cells and tumor development requires Sox2." (PMID 35582537, 2022). "In evidence, conditional knockout of SOX2 in a mouse model of osteosarcoma resulted in a dramatic reduction in tumour development supporting the role of this stemness gene in maintaining tumour growth and providing evidence towards a population of cells with stem-like features in osteosarcoma." (PMID 33799834, 2021). "Furthermore, higher percentage of SOX2-positive tumor cells positively correlates with the presence of metastasis in osteosarcoma patients, suggesting that SOX2 may be a potential prognostic marker for metastasis in osteosarcoma patients." (PMID 28934267, 2017). "Thus, our previous work demonstrates that Sox2 antagonizes Hippo signaling in osteosarcoma." (PMID 27528232, 2016). "For instance, research conducted by Zhiqiang Zhao and colleagues has demonstrated that DHM can inhibit the tumorigenesis of osteosarcoma by modulating the P38 (MAPK) and AMPKα/GSK3β/Sox2 signaling pathways." (PMID 40756986, 2025). "LPCAT1 or SOX2 overexpression promoted malignant behaviors and cholesterol metabolism (free cholesterol/total cholesterol levels, SREBP1/INSIG1 expression) of osteosarcoma cells, while shSOX2 or shLPCAT1 did the opposite." (PMID 41358198, 2025). "Of the four osteosarcoma cell lines tested, 143B and HOS, which exhibit high SOX2 expression, were able to efficiently form tumor spheres using a standard protocol." (PMID 39994220, 2025). "Through integrated analysis of clinical samples, molecular biology experiments, and animal models, we demonstrated that both SOX2 and LPCAT1 are significantly overexpressed in osteosarcoma tissues and cell lines compared to normal controls." (PMID 41358198, 2025). "In the previous work, we demonstrated the important role of AKT in regulating the stability of SOX2 protein and the important role of the AKT-SOX2 axis in osteosarcoma stemness." (PMID 39994220, 2025).
osteosarcoma (continued). "Scatter plots of 20 matched patient pairs showed higher SOX2 and LPCAT1 mRNA in osteosarcoma tissues and adjacent normal tissues." (PMID 41358198, 2025). "Across cell models, qRT-PCR showed higher SOX2 and LPCAT1 transcripts in osteosarcoma lines (MG-63, 143B, U2OS, MNNG/HOS) than in the human osteoblastic line hFOB 1.19." (PMID 41358198, 2025). "Through modulating the EGFR/STAT3/SOX2 axis, DUSP3 restrains osteosarcoma cell growth, migration, invasion, and stemness." (PMID 39744427, 2025). "We found that DUSP3 affected osteosarcoma proliferation, migration, and invasion by regulating the Epidermal Growth Factor Receptor (EGFR)/STAT3/SOX2 axis." (PMID 39744427, 2025). "DUSP3 impairs osteosarcoma cells proliferation, migration, invasion, and stemness through regulating the EGFR/STAT3/SOX2 axis." (PMID 39744427, 2025). "SOX2 and LPCAT1 expression in osteosarcoma tissues and cell lines was assessed via qRT-PCR and Western blot." (PMID 41358198, 2025). "In conjunction with our earlier in vitro research, we can infer that DUSP3 inhibits osteosarcoma development and lung metastasis in vivo through regulating EGFR/STAT3/SOX2 axis." (PMID 39744427, 2025). "The Sox2–Hippo axis has been shown to directly inhibit Neurofibromatosis Type 2 (NF2) protein and activate YAP, driving cell plasticity in both osteosarcoma and GBM cell lines." (PMID 38607003, 2024). "In osteosarcoma cell lines and patient‐derived spheres, WNT5B is enriched in stem cells and induces the expression of the stemness gene SOX2." (PMID 38689429, 2024). "Meanwhile, osteosarcoma cells with overexpressed TBL1XR1 had higher expression of stemness markers including ABCG2, BMI1, SOX2, NANOG, and OCT4, indicating that TBL1XR1 endowed osteosarcoma cells with stem cell-like properties." (PMID 38347836, 2024). "We found that osteosarcoma cells overexpressing EID3 generated more osteospheres and promoted cell invasion and had high expression of Sox2 and the stem cell marker CD133." (PMID 36071872, 2022). "In contrast, these pluripotency factors were heavily downregulated in the osteosarcoma line MG-63-DX-R, and the chondrosarcoma line T-CDS-17#4-DX-R showed lower SOX-2 levels than its parental cell line." (PMID 35742867, 2022). "ERK signaling also seems to participate in the acquisition of stemness features in osteosarcoma (expression of CD24, CD90, CD133, Nanog, SOX2, Oct4) mediated by miR-155; moreover, ERK inhibition with U0126 repressed expression of those markers." (PMID 36232719, 2022). "This SOX2-Hippo axis has been shown to directly inhibit NF2 and activate YAP, driving cell plasticity in both osteosarcoma and GBM cell lines." (PMID 35119068, 2022). "Previous studies have suggested that transcription factors OCT‐1, AP1, SP1, TNF, SOX2, SOX4, and MYC play an important role in the proliferation of osteosarcoma cells." (PMID 34185412, 2021). "Our RT-qPCR data revealed that mRNA levels of stemness-related markers, such as NANOG, SOX2, CD44, and CD133, were significantly downregulated in JAGGED1-silenced osteosarcoma cells." (PMID 34725550, 2021). "In osteosarcoma cells, YAP1 can regulate the expression of SOX2 by binding to two distinct DNA binding sites upstream and downstream of the SOX2 gene." (PMID 34199594, 2021). "The levels of both lncRNAs are positively correlated with the mRNA expression of CD133, SOX2 or CD90, and their upregulation in osteosarcoma cells led to an increase in the formation of sarcospheres." (PMID 34198693, 2021). "In conjunction with the stem cell transcription factor Sox2, KIBRA plays an important role in maintaining cancer stem cell (CSC) properties and tumorigenicity in osteosarcomas." (PMID 30042827, 2018). "Cisplatin and doxorubicin consistently reduce SOX2 and OCT4 expression in patient-derived osteosarcoma cells." (PMID 28934267, 2017).
osteosarcoma (continued). "Cancer stem cells (CSCs) are responsible for the resistance of osteosarcoma to chemotherapy and OCT4, SOX2 and SSEA4 have been used to identify CSCs in osteosarcoma." (PMID 28934267, 2017). "We also verified that cisplatin and doxorubicin reduce the expression of SOX2 and OCT4 in osteosarcoma cells." (PMID 28934267, 2017). "SOX2 and OCT4 are more expressed in tumor cells isolated from osteosarcoma patients after chemotherapy treatments, compared to tumor cells isolated from the same patients before chemotherapy." (PMID 28934267, 2017). "Transcriptome sequencing revealed that DUSP3 expression level was closely related to the STAT3/SOX2 signaling pathway, which may be the specific mechanism by which DUSP3 restrains the malignant behaviors of osteosarcoma." (PMID 39744427, 2025). "To determine whether AKT-regulated SOX2 stability is dependent on phosphorylation at T116 in osteosarcoma, we established stable 143B cell lines expressing FLAG-tagged SOX2 or its mutants (T116A and T116D) and treated them with MK2206." (PMID 39994220, 2025). "Furthermore, we also analyzed the correlation of SOX2 and AKT1 proteins in 12 human osteosarcoma protein profiling sequencing from the Orthopedic Oncology Database of Shanghai Changzheng Hospital." (PMID 39994220, 2025). "Western blot was used to detect the protein levels of SP1, Wnt, β-catenin, c-Myc, and SOX2 in osteosarcoma cells with or without GABPB1-AS1 silencing." (PMID 35342417, 2022). "Moreover, apatinib was demonstrated to enhance the sensitivity of osteosarcoma cells to doxorubicin and inhibited the doxorubicin-induced stemness phenotype through STAT3/Sox2 pathway inactivation." (PMID 36387068, 2022). "Finally, we found that the pluripotency factors SOX-2 and OCT-4 were upregulated in the osteosarcoma resistant lines 143-B-DX-R and Saos-2-DX-R, compared to their parental cells." (PMID 35742867, 2022). "Therefore, the exposure of osteosarcoma CSCs to MSCs result in an increased expression of stem factors (i.e., Nanog, OCT4 or SOX2) and enhanced sphere formation potential." (PMID 34198693, 2021). "In addition, NPJ4+Apa significantly inhibited the expression of osteosarcoma stem cell signatures, such as CD133, CD117, and SOX2, in 143B-derived tumor spheroids." (PMID 32973147, 2020). "SOX2 could act as a survival factor and impart CSC properties to osteosarcomas by antagonizing pro-differentiation Wnt signaling pathway." (PMID 30517668, 2020). "Of note, while SOX2 is supposed to bind the 3′ untranslated portion of WWC1 mRNA in osteosarcoma, multiple SOX2 binding peaks are identified in the upper region of WWC1 in ESCC TT cells, suggesting SOX2 can regulate the Hippo‐YAP1 signaling in a context‐dependent manner." (PMID 31560173, 2019). "EGCG could inhibit SOX2OT V7 which is closely related to pluripotency regulator SOX2 of CSCs, therefore, we speculated that EGCG would exert certain inhibitory effect on osteosarcoma stem cells (OSCs)." (PMID 29475441, 2018). "In this study, we show that primary tumor cells directly isolated from osteosarcoma patients after (POST) chemotherapy treatments express higher levels of SOX2 and OCT4 than primary tumor cells directly isolated from osteosarcoma patients before (PRE) chemotherapy treatments." (PMID 28934267, 2017). "As the in vitro environment is known to alter the markers expression in cells in culture, we investigated SOX2 expression in cells directly isolated from the tumor site of osteosarcoma patients, without having contact to the culture microenvironment." (PMID 28934267, 2017). "The expression of TSSC3 was low in osteosarcoma spheres and the overexpression of TSSC3 downregulated the expression of the stem cell markers Oct3/4, Nanog, and Sox2, decreased the clone formation rate, and induced apoptosis, suggesting that TSSC3 plays a suppressive role in osteosarcoma spheres." (PMID 28115942, 2016).
osteosarcoma (continued). "Interestingly, genes which are targets of YAP are decreased in TZD-treated cells with a concurrent decrease in the nuclear localization of Sox2 and YAP, suggesting that TZD treatment in osteosarcomas restores the effect of tumor suppressive Hippo signaling." (PMID 27528232, 2016). "Remarkably, the osteosarcoma U2OS cells internalized significant amount of EVs and the incubation with EVs led to an increase in the expression of EMT genes Zeb1 and Snail and of the stem cell markers Nanog, Oct4 and Sox2." (PMID 24404144, 2014). "Therefore, identification of TSCs based on POU5F1, SOX2, or NANOG expression remains controversial, at least in osteosarcoma." (PMID 22870217, 2012). "Moreover, the treatment of osteosarcoma cells with recombinant LIF protein improved sphere-formation, augmented their invasiveness and increased the expression of CSC-related genes, such as CD133, SOX2, Nanog and OCT4." (PMID 34198693, 2021). "Therefore, in this study, SOX2, OCT4, and SSEA4 have been used to identify CSCs in osteosarcoma." (PMID 28934267, 2017). "Methotrexate, on the other hand does not alter SOX2, OCT4 expression and increases SSEA4 expression in primary osteosarcoma cells." (PMID 28934267, 2017). "We also verified that cisplatin and doxorubicin reduce the expression of SOX2 and OCT4 in primary osteosarcoma cells whereas methotrexate does not alter SOX2 and OCT4 expression, however it increases SSEA4 expression in primary osteosarcoma cells." (PMID 28934267, 2017). "In osteosarcoma stem cells, the abolishment of Sox2 expression has a similar effect on cell proliferation arrest as the abolishment of YAP, a fact that comes as no surprise, since YAP is a direct target of Sox2 in osteoblasts." (PMID 36833308, 2023).
colon carcinoma (75 papers, 2008 to 2025). "Activation of the stemness factor SOX2 in Sox9-defective colon cancers is linked to EMT induction and an enhanced metastatic phenotype." (PMID 40179020, 2025). "Our findings are in contrast to our previous study demonstrating that high SOX2 density was significantly associated with poor prognosis in patients with stage III colon cancer." (PMID 32365581, 2020). "Our previous study on a cohort of stage III colon cancer patients demonstrated high SOX2+ cell densities were associated with poor prognosis." (PMID 32365581, 2020). "The overexpression of SOX2 was associated with the progression and a poor prognosis in colon cancer." (PMID 31186640, 2019). "The prior investigation of high-abundance miRNAs in rat colon tumors highlighted a role for c-Myc, Oct-3/4, and Sox2, whereas the present work has implicated a fourth ‘defined factor’ for pluripotency, namely KLF4." (PMID 23006636, 2012). "The transcription factor SOX2, which is involved in the induction of pluripotent stem cells and contributes to colorectal carcinogenesis, is associated with a poor prognosis in colon cancer (CC)." (PMID 22168803, 2011). "Increasing CaSR levels, either by transfection (HT29CaSR) or by treatment with NPS R-568 reduced the stem-like phenotype in these cells by downregulating expression of pluripotency associated genes, SOX2, Nanog, Oct4, and the colon cancer stem cell marker, CD44." (PMID 25879211, 2015). "In a recent investigation of carcinogen-induced rat colon tumors, we identified a loss of multiple let-7 family members coinciding with increased expression of miRNA-binding proteins Lin28A/Lin28B, as well as the stem-cell factors c-Myc, Sox2, Oct-3/4, and NANOG." (PMID 23006636, 2012). "All AKPS primary colon tumors were SOX2 positive and displayed high tumor grade and invasive features." (PMID 40179020, 2025). "We then addressed how SOX2 overexpression altered the phenotypes of 2 independent mouse colon cancer cell lines (AKP1 and AKP2) derived from AKP tumors." (PMID 40179020, 2025). "Sox2 induces autophagic events, such as the formation of intracellular vacuoles and the activation of lysosomes in colon cancer cells." (PMID 38397988, 2024). "For instance, METTL3 stabilized the expression of SOX2 through an m6A-IGF2BP2-dependent mechanism in colon cancer." (PMID 36793593, 2023). "Research suggested that the aberrant expression of transcription factors such as KLF14 and SOX2 in colon cancer can affect the occurrence and progression of colon cancer by affecting the expression of downstream genes." (PMID 36755247, 2023). "In colon cancer, enhanced SOX2 expression reversed the downregulation of CD133 and CD44 and the upregulation of E-cadherin 58, and inhibition of SOX2 decreased Snail expression, leading to a decrease in the invasive migratory capacity of cells." (PMID 37213675, 2023). "In colon cancer, tumor cells with high SOX2 expression have an enhanced sphere-forming ability and are accompanied by elevated expression of the CSC markers CD44 and CD2447." (PMID 37213675, 2023). "PPARβ/δ activation keeps neuronal and colonic cancer stem cells in an proliferative, undifferentiated state via the induction of Sox2 and Nanog, which, in the case of colon cancer, contributes to metastasis formation in response to fatty-acid intake." (PMID 35954274, 2022). "Studies in colon carcinoma have shown that METTL3 stabilizes the expression of SOX2 by an m6A-IGF2BP2-dependent mechanism." (PMID 32391379, 2020). "Our data demonstrate that, besides cMyc, FUT9 expression is correlated with Sox2 expression both in murine and human colon cancer cells." (PMID 32927726, 2020). "In a previous study, we observed that high SOX2+ cell density was an independent prognostic marker for poor survival in patients with stage III colon cancer." (PMID 32365581, 2020). "A current clinical trial is now examining the relationship between SOX2 expression and colon cancer aggression in biopsy samples (NCT01589900)." (PMID 33322770, 2020).